ARG1 (arginase 1)
Diseases named in the same sentence as ARG1 in open-access papers (continued):
Sharing a sentence is not in itself a finding about the gene and the disease.
tumor (continued). "Arginase 1, which in addition to M2 macrophages in the tumor microenvironment is classically secreted by myeloid-derived suppressor cells (MDSC), has various immunosuppressive roles." (PMID 33126765, 2020). "In order to evaluate the effect of PGNO-media on macrophage activation during tumor growth in vivo, we harvested tumor tissues and analyzed their expression of iNOS and Arg1." (PMID 32089766, 2020). "Although reduced NO leads to suppressed tumor cytotoxicity, Arg1‐primed TAMs promote M2 polarization and polyamine synthesis, thus enhancing tumor progression." (PMID 34766109, 2020). "M2-like TAMs secrete strongly immunosuppressive cytokines such as IL-10, TGF-β, arginase-1 (Arg1), and prostaglandins to inhibit the activity, proliferation and antitumorigenic effects of T-cells in the tumor microenvironment." (PMID 32326073, 2020). "In another study tumor-infiltrating DCs were observed to decrease the expression of CD3ζ in T-cells in ARG1-dependent manner and induced anergy in naïve CD8+ T-cells." (PMID 32499785, 2020). "MDSC recruitment can be induced by tumor-derived chemokines and cytokines, such as granulocyte-macrophage colony-stimulating factor (GM-CSF), G-CSF, interleukin (IL)-6, IL-1β, arginase 1 (ARG1), interferon (IFN)-γ." (PMID 32060421, 2020). "In another study, the NKG2D ligand RAE-1ε expressed on tumor cells facilitated the expansion and activation of MDSCs that display pronounced ARG1 activity and IL-10 production." (PMID 32793192, 2020). "Both inflammatory and tumor-derived factors are involved in the regulation of ARG1 expression in MDSCs." (PMID 32499785, 2020). "For instance, PGE2 generated by COX2 in tumor cells upregulates ARG1 expression of MDSCs through the EP4 receptor." (PMID 32793192, 2020). "There were significant differences in ARG1 expression and immunophenotype when comparing circulating MDSCs and tumor-infiltrating MDSCs." (PMID 32415175, 2020). "β-catenin has been previously demonstrated to control ARG1 and GS expression in the metabolic liver and tumor zonation." (PMID 33092030, 2020). "We confirmed changes in macrophage characteristics at the protein level, showing a significant decrease in Arg1+ macrophages (M2) with coincident increase in tumor-infiltrating iNOS+ macrophages (M1) upon T cell-specific Cyp11a1 deletion." (PMID 32680985, 2020). "Upregulation of arginase 1 (Arg1) is pro-tumoral, while induction of iNOS presents a dual role, likely depending on amount of NO, type of tumor, and concomitant presence of ROS." (PMID 33050070, 2020). "We demonstrated, using an ex vivo culture system, that tumor‐derived factors stimulate microglia to produce arginase‐1 (Arg1), a peptidase that cleaves l‐arginine into urea and ornithine." (PMID 32039522, 2020). "They cloned Gaussia luciferase under an arginase-1 promoter, whose expression seems to be activated by tumor-derived cytokines and metabolic intermediates." (PMID 32185403, 2020). "The ARG1 expression in tumors increased along with tumor grade and reflected lymph node involvement." (PMID 32932854, 2020). "Activated MDSCs suppress anti-tumor immunity by various mechanisms, including activation of inducible NO synthase and arginase-1 and induction of anti-inflammatory cytokines such as IL-10." (PMID 32320454, 2020). "Like arginase 1 in MDSCs, the assimilation of L-arginine by gut microbiota will lead to its depletion from the tumor microenvironment." (PMID 33330446, 2020). "Since MDSCs express multiple immune inhibitory molecules, including arginase 1 (Arg1) and PD-L149,51, we further examined the number of Arg1+ and PD-L1+ MDSCs in tumor-bearing mice at days 7 and 14 post tumor inoculation." (PMID 32770025, 2020). "Studies revealed that anti-tumor drugs inhibited the M2-associated genes, such as CD206, Arginase 1, CD204 and MMP2 in AOM/DSS mouse models." (PMID 33201893, 2020).
tumor (continued). "Fold-change in ARG1 increased along with tumor grade (ρ = 0.36, p = 0.031) and growing N stage (N0-N1-N2): ρ = 0.35, p = 0.031." (PMID 32932854, 2020). "Since then, many other studies confirmed that immature tumor myeloid cells express ARG1 in mice and humans with cancer and that the activity of this enzyme is involved in suppression of T-cell response." (PMID 32499785, 2020). "The immunosuppressive environment in tumor bed was confirmed by increased expression of Arg1, 24 and 48 h after PDT, and iNOS 24 h post-PDT." (PMID 32107566, 2020). "Similar to what occurred in KPC‐conditioned media treated primary microglia, we observed increased expression of Il‐1b and Arg1 in the hypothalami of tumor‐bearing animals compared to sham animals, whereas there was decreased expression of Nos2 and Tmem119." (PMID 32039522, 2020). "An important role of immunomodulatory enzymes such as Arg1 or inducible nitric oxide synthases (iNOS) as well as myeloid cells in the shaping of PDT-treated tumor environment has been recently highlighted." (PMID 32107566, 2020). "These Arg1-expressing tumor-infiltrating DCs also contribute to local arginine depletion and indirectly dampen T cell anti-tumor response." (PMID 32121028, 2020). "Of note, the mRNA levels of Arg1, Slc7a8 and Slc7a11 were substantially higher in tumor than in splenic F4/80+ cells." (PMID 32396064, 2020). "In the present study, ARG1 additionally correlated positively with tumor grade, indicative of its aggressiveness." (PMID 32932854, 2020). "The knockdown of lncRNA Pvt1 significantly reduced the immunosuppressive activity of G-MDSCs such as decreased levels of Arg1 and ROS in G-MDSCs and delayed tumor progression in tumor-bearing mice." (PMID 32443699, 2020). "Interleukin (IL)-1β and interferon gamma (IFNγ) activate STAT1 to produce ARG1 and inducible nitric oxide synthase (iNOS) and suppressive cytokines such as TGFβ to play a role in promoting tumor growth." (PMID 32325683, 2020). "Tumor-adjacent tissue had higher expression of ARG1, DDAH1, and DDAH2 and lower NOS2 than patients-matched tumors." (PMID 32932854, 2020). "Many of the suppressive machineries of MDSCs can be potentiated by tumor derived-exosomes, including expression of ARG1 and iNOS, and production of IL-10 and VEGF." (PMID 32793192, 2020). "A high level of arginase 1 (ARG1) expression by MDSCs depletes L-arginine in the tumor microenvironment, leading to downregulation of the CD3 ζ-chain of the TCR complex and proliferative arrest of T cells." (PMID 32793192, 2020). "From the literature, the existence of an “arginine paradox” has been suggested regarding roles of L-arginine and ARG1 in tumor development." (PMID 33092030, 2020). "This study confirmed there were significant differences between circulating MDSCs and tumor-infiltrating MDSCs in terms of phenotypic characteristics and ARG1 expression under GC conditions." (PMID 32415175, 2020). "Arg1 upregulation in MDSCs depletes T cells of l-arginine in the tumour milieu, limiting T cell anti-tumour activity." (PMID 33092283, 2020). "In vivo imaging of tumor macrophages revealed that in contrast to tumor periphery these cells are highly mobile within the tumor microenvironment, exhibit structural diversity and gene expression profile that includes increased ARG1." (PMID 32499785, 2020). "All these observations indicate that ARG1+ neutrophils seem to play a detrimental role in tumor progression, mainly due to immunosuppressive effects." (PMID 32499785, 2020). "CD11b+ and ARG1+ myeloid cells are co-localizing close to the tumor epithelial border, forming an envelope covering the invasive front of the tumor ROI." (PMID 33193316, 2020). "PGE2 increases the expression of Arg1 to promote tolerogenic phenotype in DCs to inhibit the proliferation of CD4+ T cells in the tumor microenvironment." (PMID 32121028, 2020).
tumor (continued). "Preclinical and clinical studies showed that treatment with tadalafil, an inhibitor of phosphodiesterase-5 (PDE5), significantly inhibited MDSCs’ suppressive functions by the downregulation of iNOS and ARG1, boosting tumor-specific immunity." (PMID 32823961, 2020). "Inhibition of CBP/EP300-BRD redirected tumor-associated MDSCs from inhibitory phenotype to inflammatory phenotype by down-regulating the genes associated with the STAT pathway and inhibiting Arg-1 and iNOS." (PMID 33027968, 2020). "It turned out that tumor cells release IL-8 that induces ARG1 exocytosis from neutrophils into extracellular milieu." (PMID 32499785, 2020). "On the other hand, calcitriol stimulated the expression of Arg1 (M2 macrophage marker) in the tumor tissue of young mice bearing 4T1 cells." (PMID 32887237, 2020). "MDSCs use vast inflammatory mediators to suppress anti-tumor immunity, e.g., arginase 1 (ARG1), transforming growth factor β (TGF-β), interleukin 10 (IL-10), and indoleamine 2,3-dioxygenase (IDO)." (PMID 31001284, 2019). "Although l‐arginine consumption by Arg1 is a well‐known immunoregulatory mechanism at work in M2 macrophages and in myeloid‐derived suppressor cells in many tumour settings, only recently has the immunosuppressive function of polyamines been unveiled in DCs." (PMID 30793469, 2019). "Next the mo-MDSCs were sorted from the groups exposed to the serum of control or tumor-bearing mice, and the level of arginase-1 (Arg-1) and inducible nitric oxide synthase (iNOS) mRNA was detected." (PMID 31395859, 2019). "Altogether, we have found that increased ARG1 expression in the primary tumor, as well as increased ARG activity in plasma correlates with poor prognosis." (PMID 31278254, 2019). "Activation of macrophages enhanced the production of TNF-α and IL-12 after two days of co-culture with tumor cells as detected by ELISA assay, while ARG1 remained unchanged among all panels except for the 3 min plasma-exposed macrophages." (PMID 31216715, 2019). "MDSCs inhibit the ability of other immune cells to kill tumor cells by producing soluble factors such as interleukin (IL)-10, transforming growth factor-β (TGFβ), arginase 1 (Arg1), and reactive oxygen species (ROS) as well as by direct cell:cell interactions." (PMID 31781510, 2019). "As shown in representative simulation images, the extracellular acidosis, created by excess tumour glycolysis, dynamically changes the macrophage phenotype represented by the Arg1 and Ccl2 expression." (PMID 31417189, 2019). "In an in vitro co-culture/radiation system using mouse and human tumor cells, Arg1-producing MDSC displayed radioprotective activity by reducing arginine and NO." (PMID 31001479, 2019). "One of the mechanisms of neutrophils in promoting tumor progression is that neutrophils can suppress CD8 + T lymphocyte antitumor response by releasing nitric oxide synthase (iNOS) or arginase 1(ARG1)." (PMID 31243628, 2019). "In addition, the ARG1 levels can be affected by tumor metabolism; lactic acid produced by tumor cells, a by-product of aerobic or anaerobic glycolysis, up-regulates the levels of ARG1 in tumor associated macrophages by stabilizing hypoxia-inducible factor 1a (HIF1a)." (PMID 30728077, 2019). "In the tumor microenvironment, TAMs preferentially express arginase-1, which competes with iNOS for L-arginine to form L-ornithine and urea." (PMID 31275860, 2019). "The soluble enzyme arginase 1 derived from tumor-infiltrating myeloid cells was also suggested to mediate T-cell suppression." (PMID 31616408, 2019). "We sorted CD11b + cells from ascites derived from the ID8 tumor model and confirmed high arginase 1 expression in these myeloid cells." (PMID 30728077, 2019). "Among various mechanisms responsible for immune suppression, arginase-1 (ARG1)-carrying small extracellular vesicles (EVs) emerge as important contributors to tumor growth and tumor escape from the host immune system." (PMID 31278254, 2019).
tumor (continued). "MDSC promote tumor growth and metastasis via various mechanisms including PD-L1-dependent direct inhibition of T cell function and amino acid deprivation by arginase-1 and iNOS." (PMID 31694706, 2019). "MDSCs are involved in tumor progression by promoting tumor proliferation, inducing vascularization, and by secretion of ARG1 and iNOS that suppress the anti-tumorigenic dendritic cells, T cell activation and natural killer (NK) cell cytotoxicity." (PMID 30781344, 2019). "Deregulation of selected genes (Arg1, C7, Lcn2, Nt5e, and Tgfb1) from preinvasive lesion to overt cancers (classical tumours and PDC) was orthogonally confirmed by qPCR." (PMID 31439856, 2019). "Tumor-infiltrating MDSCs are more immunosuppressive than splenic MDSCs, primarily due to an increase in Arg1 activity and nitric oxide production via HIF-1α in these cells." (PMID 30925926, 2019). "The therapeutic effect of the arginase 1 inhibitor on tumor growth was also observed in a pre-clinical mouse model of lung cancer." (PMID 31616408, 2019). "The presence of ARG1 or immunosuppressive cells expressing high levels of this enzyme in the tumor microenvironment has been described as the molecular mechanism leading to arginine deprivation in the tumor microenvironment." (PMID 30728077, 2019). "Arg1 promotes tumor progression by degrading arginine, an essential amino acid for T cell activation and function." (PMID 31001479, 2019). "These EVs transfer functionally active ARG1 as metabolic checkpoint molecules over a long distance to antigen-presenting cells and mitigate antitumor immune response, leading to an enhanced tumor growth in vivo." (PMID 31278254, 2019). "HSC-induced MDSCs highly expressed inducible nitric oxide synthase (iNOS) and arginase 1 mRNA and presented potent inhibitory T-cell immune responses in the tumor environment." (PMID 31614930, 2019). "In this gene-cluster we identified ARG1, which has been already associated to MDSC function in both tumor-bearing mice and cancer patients." (PMID 31533831, 2019). "Single cell RNA-Seq of patient lung tumors showed very little ARG1 in general and was elevated mainly in B cells, myeloid cells or minor group of T cells in the tumor, while ARG2 was expressed across several cell types both in normal tissue and tumors." (PMID 30728077, 2019). "In line with this, in models of lung and renal cell carcinoma, entinostat, a class I histone deacetylase inhibitor, improved the anti-tumor effect of anti-PD-1 antibodies by reducing the expression of Arg1, iNOS, and COX2 in MDSCs." (PMID 31130949, 2019). "Production of COX-2 increased MDSCs proliferation correlated to an upregulation in the expression of arginase-1 and iNOS in murine tumor-infiltrating leukocytes, thereby promoting tumor." (PMID 31275326, 2019). "Fewer genes were found deregulated when comparing EP from PDC and classical, and Arg1 and Il4ra were among the genes further upregulated suggesting that immunosuppressive myeloid cells were accumulating as tumour progressed." (PMID 31439856, 2019). "Adoptively transferred natural killer (NK) cells were shown to be converted in tumour-bearing mice by GM-CSF into CD11b+Gr1+ MDSCs, which expressed arginase-1 (ARG-1), produced reactive oxygen species (ROS) and exerted immunosuppressive activity." (PMID 30413826, 2019). "On the other hand, the M2 macrophage phenotype gene, Arg1, and two pro-angiogenesis/tumor genes (Cxcl14 and Mmp13) were identified as poor prognosis markers." (PMID 31507609, 2019). "Analysis of publicly available gene expression data sets of primary OvCa tumors from The Cancer Genome Atlas (TCGA) indicated that high ARG1 expression in the tumor corresponded to worse prognosis." (PMID 31278254, 2019). "In vitro, recombinant human arginase 1 induces cell cycle arrest and apoptosis of human tumor cell lines." (PMID 31616408, 2019). "In an OvCa mouse model, we show that blocking arginase activity mitigates ARG1-driven tumor progression." (PMID 31278254, 2019).
tumor (continued). "Similar to other tumor models, in MM patients, Arg-1, iNOS, ROS, and TNF-α were found to be overexpressed by MDSCs." (PMID 31640764, 2019). "To the best of our knowledge we are the first to report ARG1 presence in tumor-derived EVs, although modulating activity of ARG1 in EVs has been recently reported in non-tumor settings." (PMID 31278254, 2019). "After being recruited to tumor sites, these macrophages were reshaped into an M2 protumor phenotype (i.e., increased Arg1, Fizz1, and Mrc1 expression) to promote tumor progression." (PMID 32039025, 2019). "In mice with normal immunity, the serum IFN-γ (a Th1 cytokine) level and the tumoral expression of Arg1+ cells (M2 TAMs) were elevated, but the IL-4 (a Th2 cytokine) level and the expression of iNOS+ cells (M1 TAMs) were diminished after tumor inoculation." (PMID 31781219, 2019). "Tumors of Arg-1-deficient mice were about half the size comparing with those of wild-type mice, suggesting that Arg-1 in TAMs has an essential role in tumor growth by producing polyamines to promote cell proliferation." (PMID 30766614, 2019). "Studies in cancer patients support an immunosuppressive role for ARG1 in evading and escaping the anti-tumor immune response." (PMID 30728077, 2019). "MDSCs are known to inhibit Tcells through the secretion of arginase 1, iNOS, and ROS in the tumor microenvironment." (PMID 30979375, 2019). "Previous studies also established a link between hepatic autophagy, hepatocyte-derived circulating ARG1, and the systemic arginine-to-ornithine ratio, leading to reduced tumor growth in mice." (PMID 31784108, 2019). "We show that EVs distribute ARG1 from tumor cells to antigen-presenting cells in secondary lymphoid organs, suppressing antigen-specific T-cell proliferation and activation." (PMID 31278254, 2019). "High levels of arginase-1 can promote tumor growth through the production of L-ornithine and putrescine." (PMID 31275860, 2019). "In murine studies, injection of the arginase inhibitor hydroxy-nor-arginine (nor-NOHA) or Nω-hydroxy-arginine (NOHA) or genetic disruption of Arg1 in the myeloid compartment resulted in reduced tumor growth." (PMID 31057536, 2019). "In tumor bearing mice, high arginase 1 expression has been observed in myeloid cells that are Gr1 + CD11b+." (PMID 30728077, 2019). "Recent evidence suggests that the bioengineered human PEGylated arginase 1 (AEB1102) exerts additive anti-tumor effects when combined to anti-PD-1 or anti-PD-L1 in melanoma, small cell lung cancer (SCLC), and sarcoma patient-derived xenografts." (PMID 31616408, 2019). "Here, we discuss the possible protective vs. pathogenetic roles of the interplay between IDO1 and ARG1 in reprogramming immune cell functions in neoplasia and autoimmune diseases." (PMID 31354721, 2019). "LncRNA Pvt1 knockdown suppresses G-MDSC-mediated immunosuppression in vitro by decreasing the level of ROS and ARG1, and delays tumor progression in tumor-bearing mice." (PMID 31448238, 2019). "Bioengineered PEGylated arginase 1 for which the half-life was extended through PEGylation, was shown to exert anti-tumor effects in xenograft mouse models." (PMID 31616408, 2019). "Productions released by MDSCs, such as Arg1 and iNOS, can block T cells and lead to tumor progression and metastasis." (PMID 31608240, 2019). "Altogether, our studies show that tumor cells use EVs as vehicles to carry over long distances and deliver to immune cells a metabolic checkpoint molecule – ARG1, mitigating anti-tumor immune responses." (PMID 31278254, 2019). "In this scenario, iNOS is an advantage in the competition for the substrate, increasing NO production by TAMs, and preventing the production of L-ornithine and polyamines by arginase-1, besides being cytotoxic for tumor cells." (PMID 31275860, 2019).